USP8 (ubiquitin specific peptidase 8)
Description:
Hydrolase that can remove conjugated ubiquitin from proteins and therefore plays an important regulatory role at the level of protein turnover by preventing degradation. Converts both 'Lys-48' an 'Lys-63'-linked ubiquitin chains. Catalytic activity is enhanced in the M phase. Involved in cell proliferation. Required to enter into S phase in response to serum stimulation. May regulate T-cell anergy mediated by RNF128 via the formation of a complex containing RNF128 and OTUB1. Probably regulates the stability of STAM2 and RASGRF1. Regulates endosomal ubiquitin dynamics, cargo sorting, membrane traffic at early endosomes, and maintenance of ESCRT-0 stability. The level of protein ubiquitination on endosomes is essential for maintaining the morphology of the organelle. Deubiquitinates EPS15 and controls tyrosine kinase stability. Removes conjugated ubiquitin from EGFR thus regulating EGFR degradation and downstream MAPK signaling. Involved in acrosome biogenesis through interaction with the spermatid ESCRT-0 complex and microtubules. Deubiquitinates BIRC6/bruce and KIF23/MKLP1. Deubiquitinates BACE1 which inhibits BACE1 lysosomal degradation and modulates BACE-mediated APP cleavage and amyloid-beta formation.
Synonyms: KIAA0055; UBPY; HumORF8; SPG59; PITA4
Tractability: Small molecule: a structure with a bound ligand is known; a high-quality ligand is known; it has a binding pocket of medium quality. Antibody: UniProt places it where antibodies can reach, with high confidence; its Gene Ontology location is reachable by antibodies, with medium confidence. PROTAC: UniProt records ubiquitination sites on it; ubiquitination databases record sites on it; its protein half-life has been measured; a small molecule that binds it is known.
Target class: Cysteine protease; Cysteine protease CA clan; Protease; Enzyme; Cysteine protease C19 family
Gene: Protein-coding gene on chromosome 15 (50,424,372 to 50,514,421, forward strand). Ensembl gene ENSG00000138592.
Subcellular location: Cytoplasm; Nucleus; Endosome membrane; Cell membrane
Subcellular location (Human Protein Atlas): Vesicles; Cytosol; Golgi apparatus; Nucleoplasm
Pathways (Reactome):
Signal Transduction: Downregulation of ERBB2:ERBB3 signaling; Negative regulation of MET activity; Regulation of FZD by ubiquitination
Metabolism of proteins: Ub-specific processing proteases
Gene Ontology:
Molecular function: cadherin binding; cysteine-type deubiquitinase activity; K48-linked deubiquitinase activity; K63-linked deubiquitinase activity; protein binding; cysteine-type endopeptidase activity
Biological process: mitotic cytokinesis; negative regulation of lysosomal protein catabolic process; positive regulation of amyloid fibril formation; positive regulation of canonical Wnt signaling pathway; protein deubiquitination; protein K48-linked deubiquitination; protein K63-linked deubiquitination; regulation of protein localization; regulation of protein stability; endosome organization; Ras protein signal transduction; cellular response to dexamethasone stimulus; cellular response to nerve growth factor stimulus; regulation of protein catabolic process at postsynapse, modulating synaptic transmission
Cellular component: cytoplasm; cytosol; early endosome; endosome membrane; midbody; plasma membrane; postsynaptic density; acrosomal membrane; endosome; glutamatergic synapse; nucleus
Genetic constraint (gnomAD): Loss-of-function variants: 23 observed, 116.56 expected, observed/expected ratio (o/e) 0.2, 90% interval 0.14 to 0.28. The upper end of that interval is the gene's LOEUF score, 0.28, which puts it in group 1 of 6, group 1 being the genes least tolerant of losing a copy. Missense variants: 979 observed, 1,264.7 expected, observed/expected ratio (o/e) 0.77, 90% interval 0.73 to 0.82. Synonymous variants: 371 observed, 431.44 expected, observed/expected ratio (o/e) 0.86, 90% interval 0.79 to 0.94.
Cancer hallmarks: genome instability and mutations (suppresses); change of cellular energetics (promotes)
Homologues: Orthologues: macaque USP8 (98% identical), chimpanzee USP8 (98% identical), pig USP8 (92% identical), dog USP8 (90% identical), rabbit USP8 (89% identical), guinea pig USP8 (86% identical), mouse Usp8 (82% identical), rat Usp8 (82% identical), tropical clawed frog usp8 (60% identical), zebrafish usp8 (54% identical), Drosophila melanogaster Usp8 (29% identical). Paralogues in human: USP15 (20% identical), USP4 (19% identical), USP11 (19% identical), USP32 (19% identical), USP19 (18% identical), USP9X (17% identical), USP9Y (16% identical), USP2 (14% identical), USP6 (14% identical), USP24 (14% identical), USP38 (14% identical), USP34 (13% identical), and 59 more.
Diseases named in the same sentence as USP8 in open-access papers:
USP8 is named in the same sentence as 111 diseases in open-access papers, as found by Europe PMC text mining. Sharing a sentence is not in itself a finding about the gene and the disease. The quoted sentences say what the papers report.
corticotroph adenomas (36 papers, 2017 to 2025). "The reported prevalence of somatic USP8 variants in corticotropinomas shows a substantial variation, ranging from 11% to 65% across published cohorts." (PMID 40364036, 2025). "The discovery of the USP8 gene has been a major discovery in understanding the molecular mechanisms behind CD, as these mutations are widely present in corticotropinomas, with their prevalence estimated at around 35–60% of cases." (PMID 40364036, 2025). "Taken together, our data support that USP8 pathogenic variants are a marker of worse prognosis in pediatric CD and should be suspected in patients with large invasive corticotropinomas of pediatric onset." (PMID 40813536, 2025). "Among these, USP8 mutations remain the most extensively studied genetic alteration, being present in up to 60% of corticotropinomas and associated with microadenomas, lower rates of invasiveness, and higher remission rates after surgery." (PMID 40364036, 2025). "Activating mutations in the gene encoding ubiquitin-specific protease 8 (USP8), predominantly clustered within the 14-3-3 protein binding motif, has been proposed as a key driver of corticotroph adenoma formation in humans." (PMID 40943544, 2025). "The clinical relevance of USP8 mutations has been studied extensively in recent research on genetic mutations in corticotropinomas." (PMID 40364036, 2025). "But there is inconsistency regarding the role of USP8 variants in cell cycle regulation in corticotroph adenomas." (PMID 38862897, 2024). "A Retrospective study of patients with 30 functional and 20 silent corticotroph adenomas showed USP8 variants in 11 and 2 adenomas, respectively." (PMID 38862897, 2024). "In a recent study, genetic analysis of corticotroph adenomas using RNA-seq and IHC showed an increase in ASCL1expression and protein levels in both mutated and wild type USP8 among CD patients." (PMID 38862897, 2024). "Over the past years, research has shown that somatic defects in ubiquitin‐specific protease 8 (USP8) codons 718–720 are a frequent genetic cause of Cushing's disease, found in up to 62% of corticotropinomas." (PMID 39688352, 2024). "Hotspot mutations in ubiquitin-specific peptidase (USP8) are reported in 11–62% of sporadic corticotroph adenomas." (PMID 38862897, 2024). "The main clinical findings in the patients with corticotropinomas harboring USP8 variants were the prevalence of microadenomas, more frequent recurrence after successful surgery and the prevailing of SST5 and SST2 receptors’ expression." (PMID 39684597, 2024). "When analyzing our own data and data from other researchers, we noticed the duality of USP8-mutated corticotropinomas’ clinical manifestations." (PMID 39684597, 2024). "Among the somatic variants, the USP8 gene variant is the most common, found in 35-62% of corticotropinomas." (PMID 39512978, 2024). "In summary, the studies investigated the association of USP8- variants and clinical manifestations as well as clinical outcomes of the corticotroph adenomas are partly inconsistent." (PMID 38862897, 2024). "Research published over the last eight years has established that somatic defects in codons 718–720 of USP8 (exon 14 in NM_005154.5) are the most frequent genetic cause of CD, being found in 21–62% of corticotropinomas." (PMID 38067388, 2023). "Since corticotroph adenomas harboring USP8 mutations are scarcely methylated at the first promoter, adenomas of Cushing disease are likely to utilize the first promoter to transcribe the POMC gene." (PMID 36834633, 2023). "A small number of non-USP8-driven corticotropinomas are due to somatic hotspot variants in USP48 or BRAF; the latter is a well-known mutational hotspot in cancer." (PMID 38067388, 2023). "An early study detected somatic mutations of USP8 genes in 4 out of 10 corticotroph adenomas, while another study showed that 36% of 134 functioning corticotroph adenomas had mutations in the USP8 gene." (PMID 36834633, 2023).
corticotroph adenomas (continued). "In USP8 wild-type ACTHomas, the p.Met415 variant within the catalytic domain of USP48 has been identified." (PMID 34220707, 2021). "The presence of somatic USP8 driver mutations in a significant portion of corticotroph adenomas represents a novel and unique mechanism leading to ACTH excess." (PMID 33515368, 2021). "The most common genetic cause of ACTHomas is the somatic ubiquitin-specific protease 8 (USP8) variant within the 14-3-3 binding motif, which accounts for approximately 20–60% of these tumors." (PMID 34220707, 2021). "Since then, genetic sequencing of the USP8 mutational hotspot has been carried out on hundreds of corticotropinomas." (PMID 34439178, 2021). "The most frequent somatic mutations in paediatric CD have been detected in the USP8 gene that was identified in 31–63% of corticotroph adenomas." (PMID 33515368, 2021). "Two recent studies were able to distinguish secreting corticotroph adenomas from silent (macro) corticotroph adenomas, the former harbouring USP8 mutations and the latter showing an USP8 wild type." (PMID 34478014, 2021). "While screening for USP8 mutations, we found a novel USP8 genetic variant p.Gly664Arg (G664R) in one corticotropinoma." (PMID 34439178, 2021). "Increased EGFR expression in corticotroph adenomas has been attributed to recently identified somatic mutations in ubiquitin-specific peptidase 8 (USP8), a deubiquitinase enzyme that protects EGFR from degradation." (PMID 32012988, 2020). "The USP8 mutation is unique to corticotroph adenomas among all subtypes of PAs, and cells with the USP8 mutation secrete higher levels of adrenocorticotropic hormone than cells with the wildtype USP8 protein." (PMID 32652004, 2020). "The tumor size and patient age were correlated with the TIIC abundance, and the ubiquitin-specific protease 8 (USP8) mutation in corticotroph adenomas influenced the intratumoral TIIC distributions." (PMID 32652004, 2020). "The function of EGFR in the adenomaigenesis of CD has been highlighted by the finding of ubiquitin specific peptidase 8 (USP8) mutations in 35–62% of corticotroph adenomas." (PMID 31798535, 2019). "We next examined the prevalence of USP48 and BRAF mutations in additional corticotroph adenomas with wild-type USP8 by targeted sequencing." (PMID 30093687, 2018). "We previously reported that USP8-mutated corticotroph adenomas are small in size and have higher ACTH production." (PMID 30093687, 2018). "In this study the authors report USP48 and BRAF are frequently mutated in USP8 wild-type corticotroph adenomas, and cause Cushing’s disease mainly through promoting the promoter activity of POMC." (PMID 30093687, 2018). "In summary, our study identified frequent BRAF and USP48 mutations in corticotroph adenomas carrying wild-type USP8 and indicated that these mutations cause Cushing’s disease mainly by activating POMC gene transcription and increasing plasma ACTH levels." (PMID 30093687, 2018). "Previous studies have demonstrated that the USP8 mutation causes corticotroph adenomas mainly through activating the EGFR–MAPK signal cascades." (PMID 30093687, 2018). "Missense mutations of USP48, including M415I/V substitutions, were also identified as most frequent mutations in USP8 wild-type corticotroph adenomas." (PMID 30093687, 2018). "In corticotroph adenomas,USP8 mutations were more likely in females, smaller-sized tumors, and microadenomas." (PMID 28529722, 2017). "The identification of recurrent somatic mutations that lead to CD has been elusive until the recent discovery of somatic mutations in the ubiquitin-specific peptidase 8 gene (USP8) in 35%–62% of CD-causing corticotroph adenomas." (PMID 28487882, 2017).
corticotroph adenomas (continued). "USP8 has a 14-3-3 protein-binding site, and theUSP8 mutations found in corticotroph adenomas clustered to the 14-3-3 protein-binding motif encoded by exon 14 of the USP8 gene." (PMID 28529722, 2017). "In this work, we have shown the significant downregulation of RSPO2 (agonist) and SFRP1 (antagonist) in WNT signaling in USP8-mutant corticotropinomas, which supports our hypothesis on the role of USP8-mutation-altered WNT signaling regulation in these tumors." (PMID 39684597, 2024). "Somatic mutations in USP8 have been detected in a significant fraction of corticotropinomas." (PMID 39684597, 2024). "In the study of Seata, the USP8 variant was found in 23% of corticotroph adenomas." (PMID 38862897, 2024). "Indeed, the more frequent recurrence of USP8-mutated corticotropinomas was shown after successful neurosurgery in our study and by others." (PMID 39684597, 2024). "Different USP8 variants are identified in corticotroph adenomas." (PMID 38862897, 2024). "USP8 mutations have also been described in pediatric patients with corticotrope adenomas, but a recent study advocates that it may be less frequent than in adult patients." (PMID 35743266, 2022). "After the identification of USP8 mutations, many research groups aimed to identify other potential driver gene mutations that could clarify the tumorigenesis of USP8-WT corticotrope adenomas." (PMID 35743266, 2022). "Whole exome sequencing of corticotroph adenomas enriched with aggressive adenomas identified USP8 mutations in only 5 of 22 adenomas, but another study found EGFR expression in the cytoplasm of 29 of 52 CD adenomas, and protein expression associated with recurrence." (PMID 34867776, 2021). "This mutation exists only in corticotropinomas, suggesting that USP8 may play an important part in CD pathogenesis." (PMID 33537004, 2020). "Based on the previous research of high-frequency mutations USP8 in corticotropinoma, this study tended to explore the regulation of the EGFR pathway by HSP90 involved in the pathogenesis of the tumor, discover potential treatment for Cushing’s disease, and provide evidence for precise treatment." (PMID 33537004, 2020). "However, USP8 mutations have pleiotropic effects in both functioning and silent corticotroph adenomas, and affect the expression levels of many genes that are involved in a range of different pathways." (PMID 33574795, 2020). "Inhibition of expression of USP8 or EGFR could be a potential therapeutic target for patients with corticotropinomas carrying the USP8 mutation." (PMID 33537004, 2020). "Germline USP8 mutations, which are commonly found as somatic mutations in corticotropin-secreting adenomas, have also recently been described in a child with dysmorphic features, developmental delay, and a corticotroph adenoma." (PMID 33574795, 2020). "USP8 mutations have also been identified in silent corticotroph adenomas." (PMID 33574795, 2020). "It is interesting to note that activation of the Hedgehog pathway induces ACTH secretion in a pathway which may be deregulated in USP8 mutated corticotropinomas." (PMID 31845722, 2019). "Additionally, it has been suggested that USP-8 mutations predict the response to pasireotide in corticotroph adenomas." (PMID 30627156, 2018). "Mutations of the deubiquitinase gene USP8 occur in 35–62% of corticotroph adenomas." (PMID 30093687, 2018). "Recently, the deubiquitinase gene USP8 was found to be mutated in 35–62% of corticotroph adenomas, resulting in sustained activation of the epidermal growth receptor (EGFR), the mitogen-activated protein kinase (MAPK) pathway, and subsequent overproduction of ACTH7,8." (PMID 30093687, 2018). "Exome-sequencing studies also revealed some potential genetic lesions closely related to the pathogenic mechanism in USP8 wild-type corticotroph adenomas, including loss-of-function mutations of the glucocorticoid receptor gene NR3C17,8,11, a critical negative regulator of ACTH production." (PMID 30093687, 2018).